LEP (leptin)
Diseases named in the same sentence as LEP in open-access papers (continued):
Sharing a sentence is not in itself a finding about the gene and the disease.
infection (continued). "Upon infection with N. caninum, an increase in the number of non-hepatocytes cells staining for leptin was observed." (PMID 32709166, 2020). "A slight decrease of leptin serum levels was detected 24 h after infection in WT mice, while no alteration was observed in p40−/− mice." (PMID 32709166, 2020). "Therefore, it remains to be determined whether the early decrease in serum leptin detected upon N. caninum infection in WT mice could have also contributed to the higher frequency of IFN-γ producing cells observed in WT mice compared to p40−/− mice 24 h after infection." (PMID 32709166, 2020). "It has been described that a mutation (Tyr 1138 Ser) in tyrosine 1138 residue located in the intracellular domain of LEP-Rb isoform mediates STAT3/SOCS3 signaling, which results in decreased chemokine production and immune cells recruitment at the site of infection in mucosal gut tissue." (PMID 32824322, 2020). "No significant change in total leptin, however, comes as no surprise as we saw no significant change in total epididymal fat pad or body weight during the lifespan of infection." (PMID 31220189, 2019). "The levels of plasma adipokines (resistin, leptin, adiponectin), and other markers of inflammation (leukocytes, plasma IL-6, CRP) in the acute phase of Puumala hantavirus infection compared to the recovery phase and one year after the infection." (PMID 30517161, 2018). "Leptin levels and back fat thickness indicated bison were in a state of negative energy balance; we therefore expected higher infection intensities in animals with lower plasma leptin." (PMID 26380705, 2015). "A second immune challenge (LPS at 7–8 weeks of age), while leading to an elevation in leptin serum level in animals that were never exposed to infection before, did not alter leptin levels in the neonatally infected animals." (PMID 25620909, 2014). "Mean leptin levels, although lower in healthy individuals than those with uncomplicated SABSI, were raised in healthy individuals compared to those with complicated infection." (PMID 25398383, 2014). "LEP and LEPR participate in the immunological response during infection." (PMID 21943151, 2011). "Leptin (LEP) and its receptor (LEPR) participate in the immunological response during infection." (PMID 21943151, 2011). "However, the role of leptin in the immune response to infection is not straightforward, and it can either be beneficial or harmful depending upon the nature of the infection." (PMID 39428707, 2025). "Chronic leptin supplementation completely reversed mortality, even though these mice ate less food and lost more weight, while acute leptin supplementation prior to infection had no rescue effect." (PMID 39480494, 2024). "Similarly, plasma leptin levels increased over 20-fold from a baseline mean of 3.5 ng/mL to 79.4 ng/mL in infected ARS-Fp-S line fish, indicating potential utility as infection biomarkers." (PMID 37928534, 2023). "However, although IL-6 also induces leptin production, leptin levels were not significantly altered after infection with Brucella abortus." (PMID 33071987, 2020). "In the lethally susceptible p40−/− mice, no decrease in serum leptin was observed upon infection with N. caninum, but a decrease in leptin mRNA expression levels in the adipocyte fraction and stromal vascular fraction cells was observed, similar to the one observed in WT mice." (PMID 32709166, 2020). "In addition to this, a mutation (Tyr 1138 Ser) in tyrosine 1138 residue located in the intracellular domain of LEP-Rb isoform mediates STAT3/SOCS3 signaling, which results in decreased chemokine production and immune cells recruitment at the site of infection in mucosal gut tissue." (PMID 29868503, 2018). "Leptin not only regulates appetite through a direct impact on the hypothalamus but also stimulates the proliferation of naïve T cells and promotes T helper 1 (Th1) cytokine response, both of which play critical roles in controlling MTB bacilli after host infection." (PMID 27835678, 2016).
infection (continued). "Serum leptin is a powerful biomarker of SIRS patients with or without infection." (PMID 20230641, 2010). "Indeed, a progressive increase of leptin concentration was observed in P. berghei (Swiss Tropical Institute strain)-infected C57BL/6 lean mice, and the level of leptin increased five times when compared with non-infected control mice, six days after infection." (PMID 18489748, 2008). "However, the systemic circulating leptin levels in serum were not altered during this infection." (PMID 29868503, 2018). "In addition, this infection may increase the appetite and substantially decrease the levels of nor-epinephrine and leptin, which tends to immune dysfunction." (PMID 29868503, 2018). "The RNA levels of adipogenic genes leptin and FABP4 exhibited no significant changes, while Acrp30 expression declined following infection." (PMID 39467689, 2024). "However, gene expression of adipokine leptin was not affected in both experimental (P2X4/HCV) and control (NV/HCV) groups on day 5 and day 9 of post infection." (PMID 35594248, 2022). "Analysis of RNA-seq dataset from spleens of chickens four days after intranasal infection with bursal disease virus (IBDV) showed a significant induction of TNF and TNFR1 (p ≤ 0.05); no induction of TNFR2; and no or low expression of leptin and LEPR (<1 RPKM), respectively." (PMID 31514326, 2019). "Spleens of both the resistant and sensitive lines did not express leptin mRNA and lowly expressed LEPR mRNA, regardless of infection by MDV, while mRNAs of TNF and TNFR1 were induced in the spleens of both sensitive and resistant lines (TNF, 10- and 3-fold; TNFR1, 2- and 1.5-fold, respectively)." (PMID 31514326, 2019).
renal disease (50 papers, 2010 to 2025). "Vice versa, elevated leptin levels associated with disease manifestations and administration of leptin promote the development of autoantibodies and renal disease in murine SLE." (PMID 37006245, 2023). "Again, paradoxically, in CKD patients, adipokines, adiponectin and leptin, and the ratio leptin/adiponectin, are increased, independently of traditional renal disease risk factors." (PMID 36289903, 2022). "In leptin-deficient (ob/ob) mice, leptin deficiency protected against the development of autoantibodies and renal disease, with an increase in Tregs after treatment with the SLE-inducing agent pristane." (PMID 33557015, 2021). "Leptin deficiency protected mice from the development of autoantibodies as well as renal disease, and elevated the levels of Treg cells, compared with wild-type controls." (PMID 29910742, 2018). "This association might reverse in populations with overt kidney disease, where leptin clearance is reduced." (PMID 41200622, 2025). "Several studies have investigated the association between leptin and renal diseases so far." (PMID 35619087, 2022). "This study was carried out on the assumption that common polymorphisms of the LEP may be associated with kidney disease given that serum leptin has been clinically and pathogenetically linked with markers of kidney disease." (PMID 20140086, 2010). "A further and probably a more important limitation to it is our inability to show that these polymorphisms have any effect on tissue leptin, especially since we postulated that kidney disease in this population is associated with polymorphisms of the LEP through the renal effects of leptin." (PMID 20140086, 2010). "It is therefore possible that genetic variation/s in the LEP, possibly related to variation in serum leptin concentration may be associated with markers of kidney disease such as urine albumin-to-creatinine ratio (UACR), Scr and eGFR." (PMID 20140086, 2010). "However, it has been proposed that the chronic elevation of blood leptin may be associated with altered signalling of both insulin and leptin, dysregulation of lipid metabolism, blood pressure, and kidney diseases." (PMID 36064746, 2022). "In addition, leptin may stimulate profibrotic action in the kidney by sympathetic overactivity which has been associated with the progression of renal disease." (PMID 21304902, 2011). "In regard to their potential to identify disease and its progression, patients with kidney diseases have higher levels of urinary adiponectin, lipocalin-2, leptin, galectin-3 and IL-6." (PMID 37189804, 2023). "For example, administration of leptin further increased autoantibody and renal disease development while leptin antagonism delayed disease and increased survival." (PMID 36479348, 2022). "Concerning leptin, this result is in line with most clinical studies of leptin alteration in kidney diseases in adults and children." (PMID 32182671, 2020). "The potential role of leptin in SLE that we demonstrated here is also consistent with previous reports showing that a genetic deficiency of leptin protected mice from SLE, specifically reducing the production of autoantibodies and preventing renal disease." (PMID 30169503, 2018). "There is some information about the relationship between leptin and adiponectin on other renal diseases." (PMID 28898254, 2017). "Leptin results in the development of renal disease by binding to its specific receptors in renal endothelial cells and mesangial cells." (PMID 22567283, 2012). "This study is important in two ways: firstly, its focus on the relationship between the LEP and renal disease phenotypes." (PMID 20140086, 2010). "A number of clinical and experimental studies have suggested a link between serum leptin and kidney disease." (PMID 20140086, 2010).
renal disease (continued). "By inducing the production of proinflammatory mediators and reactive oxygen species, leptin may also contribute to the inflammatory process found in renal disease and, thereby, cardiovascular complications." (PMID 40141119, 2025). "By inducing the production of proinflammatory mediators and reactive oxygen species, leptin may also contribute to the inflammatory process found in renal disease and, thereby, to CVD complications." (PMID 36289903, 2022). "Principal component 2 (PC2, orthogonal on PC1) explained 14.3% variance, with high negative loading reflected by ‘impaired glucose metabolism’ (HOMA and glucose (as well as leptin)) and high positive loading reflected by ‘kidney disease’ (creatinine and cystatin C (as well as HDL))." (PMID 32567553, 2020). "Leptin has also proven to be a factor that contributes to renal diseases." (PMID 23115723, 2012). "We show from the results of this study that genetic variation in the LEP could have significant effects on renal disease phenotypes (markers of renal disease) in indigenous Africans." (PMID 20140086, 2010). "In order to examine the involvement of Leptin and CCL22 in the development of SRNS, this study prospectively obtained serum samples from children with nephropathy prior to commencing steroid therapy." (PMID 37744450, 2023). "In addition, studies have demonstrated that Vitamin D could activate the Nrf2-Keap1 antioxidant pathway and improve renal disease in diabetic rats; it can also activate the Nrf2 signaling pathway via vitamin D receptor to ameliorate leptin-induced oxidative stress." (PMID 32184720, 2020). "However, this study discovered an inverse relationship between leptin and arterial stiffness, which was opposite not only to our study which focuses on HD patients, but also to the other studies on populations without kidney disease." (PMID 29304064, 2018).
neurodegenerative disease (39 papers, 2014 to 2026). A disorder of the central nervous system characterized by gradual and progressive loss of neural tissue and neurologic function. "Research has shown that leptin contributes to chronic inflammation, which in turn increases the risk of neurodegenerative diseases in individuals with excess adiposity." (PMID 40521397, 2025). "For instance, low levels of adiponectin and increased leptin resistance, as in obesity, were found to increase the risk for neurodegenerative diseases, which makes these hormones potential targets for neurodegenerative diseases like AD." (PMID 39994634, 2025). "The association between body adiposity and neurodegenerative disease risk suggests a pivotal role of adipokines like leptin." (PMID 39000459, 2024). "Recent research showed that leptin is associated with neurological diseases, such as neurodegenerative diseases." (PMID 37035120, 2023). "In support of this, in vitro study suggested that LEP reduced tau phosphorylation levels, which is a hallmark of neurodegenerative diseases including AD and chronic traumatic encephalopathy through the aggregation of neurofibrillary tangles." (PMID 35928129, 2022). "Age-related alterations in leptin function have implications for brain health, and specifically are correlated with an increased risk of neurodegenerative disease." (PMID 35784728, 2022). "Recent evidence indicates that like leptin, age-related alterations occur in ghrelin function which are thought to lead to an increased risk of neurodegenerative disease." (PMID 30386207, 2018). "Further mechanistic and longitudinal studies are needed to clarify the relationship between leptin dysregulation, leptin resistance, neuroinflammatory and neurodegenerative diseases." (PMID 41516046, 2025). "Given its dual role as an immune modulator and metabolic regulator, leptin remains a promising candidate for both biomarker development and therapeutic targeting in neurodegenerative diseases." (PMID 41516046, 2025). "In particular, leptin and adiponectin signaling has been shown to influence several neuropathological processes that are common in neurodegenerative diseases, particularly in AD." (PMID 39273520, 2024). "Collaborative efforts integrating clinical trials, basic research and novel drug development will be essential to fully harness the therapeutic potential of leptin, its analogs and its sensitizers in neurodegenerative diseases." (PMID 39594988, 2024). "More recent evidence points to a protective role for leptin in various neurodegenerative diseases, including AD." (PMID 39000459, 2024). "CNS inflammation or neuroinflammation is an important factor in the development and progression of neurodegenerative diseases, such as AD, PD, or HD, and inflammation can affect leptin-triggered signalling, leading to leptin resistance." (PMID 35563589, 2022). "For these reasons, targeting leptin signalling would be a potential therapy for degenerative diseases of cartilage." (PMID 33673730, 2021). "In this review, we summarize novel functions of leptin in animal models of neurodegenerative diseases." (PMID 31447640, 2019). "Understanding leptin’s mechanisms in neuronal health may offer new insights into neurodegenerative disease pathogenesis and identify therapeutic targets for intervention." (PMID 38791099, 2024). "Changes in leptin concentrations could be considered a marker of various neurodegenerative diseases or mental disorders." (PMID 37233709, 2023). "Leptin has been reported to have a neuroprotective effect on neurodegenerative diseases." (PMID 37035120, 2023). "It is thought that elevated levels of leptin in obese individuals can contribute to low-grade chronic inflammation, which could lead to degenerative diseases and autoimmune reactivity." (PMID 36431836, 2022).
neurodegenerative disease (continued). "Together this suggests not only that leptin dysfunction contributes to disease pathology, but also that the leptin system may be a novel target for treatment of other neurodegenerative diseases." (PMID 30386207, 2018). "Indeed, our understanding of the mechanisms underlying leptin’s effects in the pathogenesis of ALS is very limited, and it is fundamental to determine whether alterations in leptin’s actions take place in this neurodegenerative disease." (PMID 34638645, 2021). "Importantly, leptin and adiponectin signaling have been shown to interfere with a range of neuropathological events covering those most commonly present in neurodegenerative diseases and, in particular, in AD." (PMID 30692905, 2018). "The neuroprotective properties of several anorexigenic peptides, including leptin and GLP-1, are well established across models of neurodegenerative diseases." (PMID 42063365, 2026). "Here we assess recent evidence that supports an important regulatory role for leptin at hippocampal CA1 synapses, and we discuss how age-related alterations in this hormonal system influences neurodegenerative disease." (PMID 30386207, 2018). "Furthermore, these benefits are not restricted to AD as emerging studies suggest that other neurodegenerative diseases, like ALS, are also associated with metabolic imbalance and abnormalities in the leptin system." (PMID 33440796, 2021).